MIR381 (microRNA 381)
Synonyms: hsa-mir-381; MIRN381; mir-381
Gene: MicroRNA gene on chromosome 14 (101,045,920 to 101,045,994, forward strand). Ensembl gene ENSG00000199020.
Gene Ontology:
Biological process: miRNA-mediated post-transcriptional gene silencing
Cellular component: RISC complex
Homologues: Orthologues: chimpanzee ptr-mir-381 (100% identical), macaque MIR381 (100% identical), mouse Mir381 (100% identical), guinea pig MIR381 (95% identical), pig ssc-mir-381 (93% identical). Paralogues in human: MIR1185-2 (75% identical), MIR1185-1 (72% identical), MIR539 (72% identical), MIR494 (68% identical), MIR377 (65% identical), MIR382 (65% identical), MIR487A (65% identical), MIR154 (64% identical), MIR487B (63% identical), MIR369 (61% identical), MIR496 (61% identical), MIR323A (59% identical), and 4 more.
Diseases named in the same sentence as MIR381 in open-access papers:
MIR381 is named in the same sentence as 2 diseases in open-access papers, as found by Europe PMC text mining. Sharing a sentence is not in itself a finding about the gene and the disease. The quoted sentences say what the papers report.
esophageal cancer (1 paper, 2016). A primary or metastatic malignant neoplasm involving the esophagus. "It has also been suggested that dysregulation of two proteins, IL4 and CD40, leads to dysfunction of cell proliferation in mantle cell lymphoma, and dysregulation of MIR381 leads to dysfunction of proliferation in esophageal cancer." (PMID 26897165, 2016).
MIR381 also shares sentences with these, for which no sentence is quoted: mantle cell lymphoma (1 paper).